CASP1 (caspase 1)
Diseases named in the same sentence as CASP1 in open-access papers (continued):
Sharing a sentence is not in itself a finding about the gene and the disease.
Obesity (81 papers, 2012 to 2026). Accumulation of substantial excess body fat. "Inflammation-associated lipid metabolism is associated with metabolic disorders suggesting an association between Caspase-1 regulated lipid metabolism and obesity-associated inflammation." (PMID 38918843, 2024). "In our study, we observed a positive correlation between Caspase-1 expression and obesity and its association with adipogenesis." (PMID 38672517, 2024). "Our study proposes the downregulation of Caspase-1 as a promising strategy for mitigating obesity and its associated metabolic disorders." (PMID 38672517, 2024). "The link between lipid metabolism and caspase-1 is also supported by the fact that caspase-1-deficient mice develop obesity." (PMID 34502478, 2021). "The reduction in the NLRP3 inflammasome and CASP-1 proteins by exercise training reinforces the idea that the NLRP3 inflammasome detects danger signals associated with obesity and contributes to obesity-induced inflammation." (PMID 32624568, 2020). "Despite unequivocal evidences causally link IL-1β to the development of obesity-associated comorbities, IL-18, also activated by caspase-1, has been shown to ameliorate the development of obesity and insulin resistance." (PMID 30619282, 2018). "The NLRP3 inflammasome plays a substantial role in sensing obesity-associated inducers of caspase-1 activation and therefore regulates the magnitude of inflammation." (PMID 27686325, 2016). "Recent studies in animal models demonstrate that obesity is associated with progressive caspase-1 activation in adipose tissue." (PMID 23483669, 2013). "Additionally, pyroptosis, a caspase-1-dependent programmed cell death, is thought to be triggered by OA-related risk factors such as obesity-associated cholesterol thus promoting joint degradation which is likely accelerated in individuals with obesity." (PMID 38918843, 2024). "Additionally, caspase-1, -2 or caspase-12 deficient mice have shown alterations in metabolism and the development of obesity, with specificities for each caspase." (PMID 38824481, 2024). "Previous experiments demonstrated that Caspase-1 deficiency promotes adipogenesis through Atg7-mediated autophagy; we established an animal model by subjecting mice to a high-fat diet from week 8 until week 20 to investigate the impact of Caspase-1 deficiency under obesity conditions in vivo." (PMID 38672517, 2024). "In addition, Caspase-1 deficiency resisted against high-fat diet-induced obesity and glucose intolerance." (PMID 38672517, 2024). "However, another study has reported opposite results, suggesting that Caspase-1-deficient mice were more susceptible to high-fat diet-induced obesity and increased inflammation, primarily through the CCL2/C-C chemokine receptor 2 (CCR2) axis in adipose tissue." (PMID 38672517, 2024). "Caspase-1-deficient mice develop obesity depending on age and sex when kept on high-fat diet." (PMID 38824481, 2024). "Furthermore, the study suggests an association between the IL-1β/Caspase-1 cytokine cascade and the pathogenesis of early-stage nephropathy in relation to obesity and diabetes." (PMID 37375705, 2023). "While several studies performed on knockout/null mice models fed a high-fat diet have shown the therapeutic potential of caspase-1, -8, -11, -12 deficiencies in obesity, it is unclear if or how the use of therapeutic inhibitors would translate in a clinical setting." (PMID 34654807, 2021). "In support of this it has been shown that caspase-1 deficient mice develops obesity." (PMID 32143623, 2020). "Moreover, it has been reported that in mouse with caspase-1 knocked out, obesity develops similar to mice with IL-18 deficiency." (PMID 32463311, 2020). "According to these data, caspase-1 inhibition may represent a novel therapeutic target in clinical conditions associated with obesity and insulin resistance because its deletion would inhibit the genesis of obesity." (PMID 32545788, 2020).
Obesity (continued). "The literature has already demonstrated the elevated mRNA expression of caspase-1 and IL-1β in patients with obesity and diabetes compared to eutrophic patients." (PMID 40004007, 2025). "TIRAP, TNFRSF1A, CASP1, CSF1, and ITGAM are associated with the development of type 2 diabetes, a condition linked to obesity." (PMID 39194753, 2024). "Studies have highlighted the correlation between Caspase-1 and inflammation in obesity, elucidating its essential role in the biological functions of adipose tissue." (PMID 38672517, 2024). "aimed to assess the relationship between IL-1β/Caspase-1, insulin sensitivity and early-stage obesity-related renal damage, namely hyperfiltration." (PMID 39469576, 2024). "IL-18, another important inflammatory factor produced by Caspase-1, is increased in obese individuals, and IL-18−/− mice exhibit obesity and insulin resistance." (PMID 38672517, 2024). "In this study, we validated the correlation of Caspase-1 with obesity and adipogenesis in human and mouse tissues and cells." (PMID 38672517, 2024). "Nevertheless, these studies indicate an intimate relationship between Caspase-1, lipid metabolism, and obesity." (PMID 38672517, 2024). "However, caspase-1 deficient mice have increased susceptibility to high-fat-diet-induced adiposity, with increased subcutaneous and total body adipose tissue volumes, promoting inflammatory macrophage infiltration in adipose tissues which in turn accelerates obesity-associated inflammation." (PMID 38918843, 2024). "In this study, the reduction of the NLRP3 inflammasome and the CASP-1 proteins by exercise training, supports the idea that the NLRP3 inflammasome detects danger signals associated with obesity and contributes to obesity-induced inflammation." (PMID 36358820, 2022). "In most studies, NLRP3 and caspase-1 KO mice were found to be resistant to HFD-induced obesity and insulin resistance." (PMID 36065376, 2022). "When combined with other assays to measure inflammation, this caspase-1 biosensor mouse model can be extremely useful to perform tissue-specific drug discovery that would improve complications of obesity impacting specific tissues." (PMID 35466363, 2022). "The pro-inflammatory cytokine TNF-α was another crucial factor for the activation of caspase-1-dependent hepatocyte pyroptosis in patients with obesity and NASH." (PMID 36324154, 2022). "More detailed studies can provide deeper knowledge on the more specific roles of WAT and heart in inflammation in obesity and how tributyrin can affect caspase-1 activation." (PMID 35466363, 2022). "Regarding obesity, it is observed that expressions of caspase-1 and IL-1β, as well as a caspase-1 activity, are markedly increased in white adipose tissue of diet- or genetically-induced obese mice." (PMID 34202842, 2021). "Sirtuin 1 (SIRT1), a deacetylase that protects from obesity and regulates metabolism, has been identified as caspase-1 substrate." (PMID 32545788, 2020). "Obesity activates inflammasome NLRP3 and increases IL-1β through activation of caspase 1 and causes insulin resistance and reduction in fat oxidation." (PMID 33113859, 2020). "Caspase-1 expression in inflammasome was shown to be upregulated in the adipocytes of obese patients and that, instead, inhibition of caspase-1 can reduce weight gain in animal models, such as in mice with induced obesity." (PMID 32545890, 2020). "Under dyslipidemic and inflammatory conditions such as hyperlipidemia, hypercholesterolemia, or obesity, caspase-1 activation leads to the upregulation of the inflammasome pathway, activated by elevated lipids or inflammatory mediators, such as DAMPs, in ECs." (PMID 33339328, 2020). "This offers another possibility for the contradictory results in the obesity phenotypes detected in Casp-1-/- mice." (PMID 32545788, 2020). "In both mouse and human adipocytes during cellular differentiation and obesity development, caspase-1 levels are found to be increased." (PMID 32545788, 2020).
Obesity (continued). "Genetic ablation of NLRP3 prevented obesity-induced inflammasome and caspase 1 activation in the liver as well as improved insulin sensitivity." (PMID 32992548, 2020). "By using Nlrp3−/−, Nlrc4−/−, Casp1/11−/−, and WT obesity-prone C57BL/6 mice, another study concluded that the NLRC4 inflammasome, associated often with obesity, has a more important role in BC progression than the NLRP3 inflammasome." (PMID 31661891, 2019). "In NLRP3 knockout mice, elimination of NLRP3 ameliorated obesity-induced inflammation and insulin resistance, and caspase-1 knockout mice also improved glucose tolerance and insulin sensitivity than wild-type mice after feeding a high-fat diet." (PMID 29497383, 2018). "Reduced IL-1β secretion and caspase-1 activation; inhibited diet-induced IL-1β and caspase-1 expression from obesity, NASH, adipose tissue inflammation, and insulin resistance." (PMID 29312290, 2017). "Knockout of the NLRP3 inflammasome (NLRP3−/−, ASC−/−, and caspase-1−/−) significantly protected mice from HFD-induced obesity, increased adiposity, insulin resistance, glucose intolerance, and inflammation." (PMID 26980705, 2016). "Using a fluorescent probe for active CASP1, we also found that obesity-induced CASP1 activation was significantly reduced in CD45+ tumour-infiltrating leukocytes from NLRC4-deficient DIO mice compared with WT DIO mice." (PMID 27708283, 2016). "NLRP3 has been recently shown to play a key role in the pathogenesis of insulin resistance and obesity, and is regulated by compounds such as ceramide, which induce IL-1β processing via caspase-1 activation." (PMID 27812198, 2016). "Recent reports suggest that activated ceramide induces caspase-1 activation, IL-1β production in an Nlrp3 inflammasome dependent mechanism in obesity or acute lung injury." (PMID 26980705, 2016). "Activation of caspase-1 is required for optimal IL-1α and IL-1β maturation and secretion, with growing evidence implicating uncontrolled caspase-1 activation to be responsible for the pathophysiology of obesity and type 2 diabetes." (PMID 25849717, 2015). "Consistent with the causal role of NLRP3 inflammasome activation in the development of inflammation, deletion of Nlrp3 in mice, prevents obesity-induced caspase-1 activation." (PMID 23483669, 2013). "Another study displays that it can inhibit obesity-induced excessive activation of Caspase-1 in stellate sympathetic ganglion, whereas activated Caspase-1 can cleave GSDMD into C- and N-terminal, in which GSDMD-NT, as the pyroptotic executioner, induces proinflammatory cell death." (PMID 40915382, 2025). "As a critical inflammasome component, Caspase-1 influences the inflammatory milieu in obesity." (PMID 38672517, 2024). "Although in vivo experiments cannot completely rule out the role of Caspase-1 deficiency in macrophages and inflammation, the enhancement of adipogenesis likely contributes to the resistance against high-fat diet-induced obesity and glucose intolerance." (PMID 38672517, 2024). "In particular, genes such as IGFBP2 and CASP1, with functions related to obesity and metabolism, may explain some of our previous findings of metabolically dysregulated fibroblasts in OA synovial tissue from obese patients." (PMID 38918843, 2024). "Mice with HFD-induced obesity exhibit increased expression of caspase-1, ASC, and NLRP3." (PMID 38681198, 2024). "Therefore, our study underscores the multifaceted impact of Caspase-1 on obesity and body metabolism, encompassing both inflammatory processes and adipogenesis." (PMID 38672517, 2024). "Intriguingly, existing research indicates a dual role for Caspase-1 in obesity." (PMID 38672517, 2024). "On the contrary, the relative abundance of PCSK9 and NLRP3 positively correlated with obesity diagnosis indices (body weight, fat mass and Lee’s index), abnormal sperm rate, pyroptosis markers including Caspase-1, GSDMD, IL-1, IL-18 and the level of lipid metabolizing hormone (TG, TC and LDL)." (PMID 37935689, 2023).
Obesity (continued). "Our work demonstrated that WD feeding led to a gradual increase in caspase-1 activation in vivo over time, indicating the potential utility of this caspase-1 reporter mouse model for measuring the onset of inflammation in models of obesity and other chronic inflammatory diseases." (PMID 35466363, 2022). "We now extend this observation in demonstrating that overweight/obesity is also associated with higher frequencies of CD16+caspase-1+ non-classical monocytes." (PMID 33114648, 2020). "Obesity induces inflammation and hence regulates caspase-1 activity." (PMID 32143623, 2020). "Different mechanisms have been proposed for the role of caspase-1 in obesity." (PMID 32545788, 2020). "Dietary saturated fatty acids (SFAs), whose intake is strongly associated with an increased risk of obesity, have been identified as potent priming agents of the NLRP3 inflammasome via TLR4 in DCs, resulting in elevated expression of pro-IL-1β, caspase-1, TLR4 and NLRP3." (PMID 32545355, 2020). "A recent report suggested that nucleotide-binding domain, leucine-rich containing family, pyrin domain-containig-3 (Nlrp3) inflammasome plays a pivotal role in obesity-induced chronic inflammation, and Nlrp3 inflammasome activates caspase-1, which induces the secretion of IL-1β." (PMID 28569167, 2017). "Thus, recent data show that NLRP3-/- knockout mice do not increase weight when fed a high fat diet, and that elimination of NLRP3 expression prevents obesity-induced caspase-1 cleavage as well as IL1β and IL18 activation." (PMID 25020064, 2014). "Deficiency in any NLRP3 inflammasome component (NLRP3−/−, ASC−/−, Casp1−/−) has shown to be protective against the development of high-fat diet-induced obesity and improves glucose homeostasis in rodent models, and protective against chronic obesity-induced pancreatic damage." (PMID 23924318, 2013). "In addition to a role in steatosis and inflammatory cytokine activity, caspase-1 also contributed to early stages of hepatic fibrosis in high fat diet-induced obesity." (PMID 23409132, 2013). "In addition, absence of caspase-1 protected mice from early stages of fibrogenesis, suggesting that caspase-1 is necessary for an initial pro-fibrotic response during obesity-induced liver injury." (PMID 23409132, 2013). "However, knocking out the Nlrp3 or Caspase-1 gene suppresses obesity-induced fat depot." (PMID 38681198, 2024). "Researchers found that NLRP3-related inflammation was activated in the fat pads of leptin-deficient mice and high-fat diet-fed obese mice and that NLRP3-dependent caspase-1 activation in hypertrophic adipocytes may induce obesity and adipocyte death through pyroptosis." (PMID 35677632, 2022). "Besides counteracting obesity, perhaps activating the H1 receptor by using betahistine, or another H1 receptor agonist, could also inhibit NLRP3/caspase-1 signaling and thus pyroptosis and brain volume loss induced by chronic antipsychotic treatment." (PMID 35615587, 2022). "Additionally, knockouts of NLRP3, ASC, or caspase-1 protect mice from diet-induced obesity." (PMID 34202842, 2021). "Indeed, genetic ablation of NLRP3 or caspase-1 prevents obesity-induced adipocyte hypertrophy, yet whether this is due to changes in adipogenesis, lipolysis and/or energy metabolism remains to be further clarified." (PMID 32545355, 2020). "For example, the adipocytes of individuals with obesity and peripheral-blood mononuclear cells of patients with depression express more NLRP3 inflammatory vesicles and caspase-1, and inhibiting caspase-1 alleviates the symptoms of both conditions." (PMID 40002422, 2025). "Emerging evidence suggests that ceramide activation plays a crucial role in triggering caspase-1 activation and IL-1β production via the NLRP3 inflammasome pathway, contributing to pathological conditions like obesity, podocyte damage, and acute lung injury." (PMID 40002829, 2025).
Obesity (continued). "A study found that exercise decreased protein expression of inflammasome components (NLRP3 and caspase-1) in bone marrow-derived macrophages (BMDM) and AT isolated from mice with diet-induced obesity." (PMID 38681198, 2024). "Caspase-1 was also associated with the regulation of glucose and lipid metabolism, making it a potential target molecule in the treatment of metabolism-related disorders, such as obesity, diabetes or osteoarthritis, cancer, and non-alcoholic fatty liver disease." (PMID 38824481, 2024). "However, some have reported contrasting results, with deficiency in NLRP3 and caspase-1 not protecting mice from HFD-induced obesity, which suggests that the presence of the NLRP3 and caspase-1 genes is not required for HFD-induced adipose tissue inflammation and glucose intolerance." (PMID 36065376, 2022). "Nonetheless, the regulation of ovarian inflammation in late obesity (16- week HFD) seems to be independent from NLRP3 inflammasome activation, as IL-18 and CASP1 mature proteins were significantly downregulated." (PMID 34805147, 2021). "The present results of our analysis in the liver indicate a site-dependent NLRP3 inflammasome regulation throughout obesity, since overexpression of NLRP3, CASP1 (p20), and IL-18 (p18) took place only at 16 week of DIO." (PMID 34805147, 2021). "A very recent work demonstrated that the absence of these three critical inflammasome components, Nlrp3, ASC, and caspase-1, in mice protects mice from HFD-induced obesity, insulin resistance, and adipocyte hypertrophy." (PMID 33167412, 2020). "In animal models of HFD-induced obesity, NLRP3, ASC and caspase-1 inhibition also ameliorated the disease." (PMID 32545788, 2020). "A previous study indicated that obesity and inflamation induced the cleavage of SIRT1 protein in adipose tissue and differentiated 3T3-L1 cells by caspase-1." (PMID 29050301, 2017). "The previously reported abundance of CLS in untreated obesity and their reduction after bariatric surgery suggest that the NLRP3-Caspase-1 axis within CLS may serve as an important mediator of the beneficial metabolic effects associated with bariatric surgery." (PMID 41645554, 2026). "Apart from demonstrating the capacity of IL-1β to predict hyperfiltration in patients with severe obesity, their study had another valuable result – patients in whom GFR did not normalize after MBS also showed failure to normalize circulating IL-1β/Caspase-1 levels." (PMID 39469576, 2024). "In our study, we observed that the absence of Caspase-1 ameliorated high-fat diet-induced obesity and improved glucose tolerance." (PMID 38672517, 2024). "Overall, these results suggest that the absence of Caspase-1 potentiates adipogenesis both in vitro and in vivo, thus highlighting its potential as a therapeutic target for combating obesity." (PMID 38672517, 2024). "In the HFD-induced obesity model, aerobic exercise effectively suppressed the activation of the NLRP3 inflammasome in the left ventricles, consequently reducing expressions of NLRP3, ASC, pro-caspase-1, and IL-1β in the myocardium." (PMID 37859981, 2023). "The knockdown of integrin α5β1 attenuated FFA-induced caspase-1 cleavage and excessive lipid accumulation, reducing HMGB1 and GSDMD-NT protein levels, indicating its participation in pro-inflammatory pyroptosis during obesity." (PMID 36145246, 2022). "Therefore, the ratio of mature caspase-1 and the level of PPARγ can be represented as an “NLRP3-accelerating index” in obesity." (PMID 33500734, 2021). "Indeed, the rapid upregulation of NLRP3 protein in early obesity (after 4- week HFD treatment) was followed by a consistent downregulation of NLRP3, IL-18, and CASP1 in late obesity (after 16- week HFD)." (PMID 34805147, 2021). "Altogether, these data show that Casp1/Casp11/NE/PR3 knockout mice were protected for developing obesity-induced adipose tissue inflammation while no clear difference was observed for the glycemic control." (PMID 32002713, 2020).